COPS7A (COP9 signalosome subunit 7A)
Description:
Component of the COP9 signalosome complex (CSN), a complex involved in various cellular and developmental processes. The CSN complex is an essential regulator of the ubiquitin (Ubl) conjugation pathway by mediating the deneddylation of the cullin subunits of SCF-type E3 ligase complexes, leading to decrease the Ubl ligase activity of SCF-type complexes such as SCF, CSA or DDB2.
Synonyms: SGN7a; CSN7A; CSN7
Tractability: PROTAC: ubiquitination databases record sites on it; its protein half-life has been measured.
Gene: Protein-coding gene on chromosome 12 (6,724,014 to 6,731,875, forward strand). Ensembl gene ENSG00000111652.
Subcellular location: Cytoplasm; Nucleus
Subcellular location (Human Protein Atlas): Nucleoplasm; Cytosol
Pathways (Reactome):
DNA Repair: DNA Damage Recognition in GG-NER; Formation of TC-NER Pre-Incision Complex
Metabolism of proteins: Neddylation
Vesicle-mediated transport: Cargo recognition for clathrin-mediated endocytosis
Gene Ontology:
Molecular function: protein binding
Biological process: protein deneddylation; protein neddylation; regulation of protein neddylation; COP9 signalosome assembly
Cellular component: COP9 signalosome; cytoplasm; cytosol; nucleoplasm; nucleus; protein-containing complex
Genetic constraint (gnomAD): Loss-of-function variants: 20 observed, 37.32 expected, observed/expected ratio (o/e) 0.54, 90% interval 0.38 to 0.78. The upper end of that interval is the gene's LOEUF score, 0.78, which puts it in group 3 of 6, group 1 being the genes least tolerant of losing a copy. Missense variants: 247 observed, 366.58 expected, observed/expected ratio (o/e) 0.67, 90% interval 0.61 to 0.75. Synonymous variants: 139 observed, 149.68 expected, observed/expected ratio (o/e) 0.93, 90% interval 0.81 to 1.07.
Homologues: Orthologues: chimpanzee COPS7A (99% identical), dog COPS7A (99% identical), guinea pig COPS7A (99% identical), macaque COPS7A (99% identical), mouse Cops7a (99% identical), rat Cops7a (99% identical), pig COPS7A (93% identical), rabbit COPS7A (83% identical), zebrafish cops7a (55% identical), Drosophila melanogaster CSN7 (42% identical). Paralogues in human: COPS7B (56% identical), EIF3M (17% identical).
Diseases named in the same sentence as COPS7A in open-access papers:
COPS7A is named in the same sentence as 11 diseases in open-access papers, as found by Europe PMC text mining. Sharing a sentence is not in itself a finding about the gene and the disease. The quoted sentences say what the papers report.
gastric cancer (2 papers, 2022 to 2024). A primary or metastatic malignant neoplasm involving the stomach. "In gastric cancer, COPS7A promotes IκBα deubiquitination via CSN-associated deubiquitinase USP15, then inactivates NF-κB signaling." (PMID 35315259, 2022). "Zheng and colleagues also found that KRT19P3 suppressed gastric tumor growth and metastasis through a COPS7A-regulated NF-κB pathway, suggesting that COPS7A acts as a suppressor of gastric cancer." (PMID 38466642, 2024).
asthenozoospermia (1 paper, 2022). "We observed that COPS7A expression was upregulated in asthenospermia, but the correlation between its expression and spermatogenesis remains to be understood." (PMID 36471356, 2022). "The mRNA expression of COPS7A was upregulated in patients with asthenozoospermia, but the expression of CUL3, KLHL7, and NEDD4 was downregulated in these patients." (PMID 36471356, 2022). "Finally, we found that the COPS7A was significantly upregulated in patients with asthenozoospermia, but CUL3, KLHL7 and NEDD4 were significantly downregulated compared with normal samples." (PMID 36471356, 2022). "A western blotting assay using 16 semen samples (including 8 asthenospermia and 8 normal samples) revealed similar results, indicating COPS7A was significantly upregulated in patients with asthenozoospermia, but CUL3, KLHL7 and NEDD4 were significantly downregulated compared with normal samples." (PMID 36471356, 2022). "The intersection among two groups of hub genes included COPS7A, CUL3, KLHL7, and NEDD4, which can be considered the main key genes in asthenozoospermia." (PMID 36471356, 2022). "A Venn analysis was used to identify four key genes based on two methods, including COPS7A, CUL3, KLHL7, NEDD4, which may be potentially important genes in asthenozoospermia." (PMID 36471356, 2022).
autism spectrum disorder (1 paper, 2023). A spectrum of developmental disorders that includes autism, and Asperger syndrome. "In line with this concept, the transcript of COPS7A was also found to be downregulated in postmortem cortical samples of subjects with autism spectrum disorder and schizophrenia." (PMID 37269073, 2023).
Chronic Lymphocytic Leukemia (1 paper, 2021). "Applying rvGWAS to a Chronic Lymphocytic Leukemia study we identified eight candidate predisposition genes, including EHMT2 and COPS7A." (PMID 33606672, 2021).
tumor (7 papers, 2019 to 2022). "Mechanistically, KRT19P3 can directly bind COPS7A and then enhance the stability of COPS7A protein, which subsequently promotes the deubiquitinylation of IκBα and then inactivates the NF-κB signaling pathway, thus suppressing tumor metastasis." (PMID 33520725, 2020). "Based on mRNA sequencing data from the TCGA database, recent publications have confirmed that COPS7A has a specific expression pattern in multiple tumor types, supporting our inference from an independent aspect." (PMID 32626751, 2020). "As a detailed case, variant bAug10 with two unique APA sites, or the transcript of COPS7A, is specifically expressed in the colon and the ovary that distinguish tumor types derived from the two tissues from other tumor types." (PMID 32626751, 2020). "The differential analysis filtered for processes driven by CD271 in tumor-initiating cells also revealed enrichment for the genes participating in nucleotide excision repair (NER, including damage recognition and repair factor XPC, DNA repair associated BRCA2, UBE2I, COPS7A, POLD3, USP45, RFC5)." (PMID 31118427, 2019). "The transcripts of COPS7A have quite different APA sites in various tissues; thus, the gene has different APA-modified patterns in various tumor types." (PMID 32626751, 2020). "By contrast, other genes, including COPS7A, TAPT1, PAPD4, C4orf3, and HMGB2, have a tumor suppressor effect, and their high expression levels characterize patients with a good survival potential." (PMID 32626751, 2020).
cancer (2 papers, 2022 to 2023). A tumor composed of atypical neoplastic, often pleomorphic cells that invade other tissues. "Among these, MLF2, COPS7A, PEX5, DDX47, STRAP and MRPL51 displayed strong correlations with USP5 in most cancer types." (PMID 37268697, 2023).
COPS7A also shares sentences with these, for which no sentence is quoted: Allergy (1 paper); ciliopathy (1); gastric tumor (1); infection (1); schizophrenia (1).